FGF2 (fibroblast growth factor 2)
Diseases named in the same sentence as FGF2 in open-access papers (continued):
Sharing a sentence is not in itself a finding about the gene and the disease.
tumor (continued). "TGFβ, Fibroblast growth factor 2 (FGF2), matrix metalloproteases 2 (MMP2) and hepatocyte growth factor (HGF) derived from CAF endow tumor cells with stronger proliferative behavior." (PMID 36922546, 2023). "FGF2 binds to four receptor tyrosine kinases (FGFR1-4) and acts in a variety of physiological and pathological processes, such as angiogenesis, tumor growth, and development." (PMID 37591843, 2023). "During the initial phases of tumor growth, the cross-talk between FGF-2 and VEGF-A is able to induce neovascularization and boost tumor progression." (PMID 37374319, 2023). "Angiogenic factors such as VEGF (vascular endothelial growth factor), FGF-2 (fibroblast growth factor 2), PDGF (platelet-derived growth factor), angiopoietins, and ephrines induce neovascularization around the tumor." (PMID 36732815, 2023). "For example, large numbers of cytokines and growth factors that stimulate angiogenesis, including VEGF, FGF-2, βFGF, PDGF, IL-8, IL-6, angiopoietin, and TGF, are released by MSCs and contribute to the development of tumor angiogenesis." (PMID 36829187, 2023). "Adrenomedullin (AM) expression induced by mast cells facilitates recruitment of endothelial cells to the tumor microenvironment, where they promote angiogenesis via secretion of VEGF, FGF-2, tryptase, and MMPa." (PMID 37370399, 2023). "Tumoral lymphangiogenesis is fostered by tumor-derived VEGF-C and other lymphangiogenic growth factors such as angiopoietin 2 and fibroblast growth factor 2, which functionally interact with VEGFR3’s downstream effectors." (PMID 38201272, 2023). "MSCs are capable of secreting several angiogenic factors (FGF-2, PDGF, VEGF, TGF-β, IL-6, IL-8, and angiopoietin-1) that facilitate angiogenesis leading to tumor-promoting features." (PMID 36674525, 2023). "By interacting with FGF2 and VEGF, fibrinogen can regulate the adhesion, proliferation and migration of tumor cells." (PMID 37541963, 2023). "iCAFs are found to secrete FGF2, which acts on the CD44 receptor of rCSC‐M, thereby maintaining tumor stemness and epithelial‐mesenchymal transition." (PMID 37743226, 2023). "In concert, tumor cells and CAFs secrete pro-angiogenic factors such as VEGF, FGF2, PDGFA and PDGFB." (PMID 37091337, 2023). "In melanoma, miR-155 derived from the tumor inhibits SOCS1 and promotes the activation of the JAK2/STAT3 signaling pathway, increasing FGF2, VEGFA, and MMP9 levels in CAFs." (PMID 37605155, 2023). "Studies have shown that angiogenesis in tumors is required for metastasis development and tumor development involving growth factors such as IL-8, VEGF (bFGF/FGF-2), and MMPs." (PMID 36555740, 2022). "In a xenograft model, TECs treated with TGF-β were more competent in promoting tumor growth than TECs treated with TGF-β and FGF2." (PMID 35130955, 2022). "FGF2 is a key member of the fibroblast growth factor (FGF) family and has been reported to play an important role in tumor progression and angiogenesis." (PMID 34738872, 2022). "In fact, CAFs directly enhance tumor angiogenesis through producing pro-angiogenic factors like vascular endothelial growth factor A (VEGFA), fibroblast growth factor 2 (FGF2), CXCL12, and PDGFC." (PMID 36465388, 2022). "The components in the TME can directly secrete metabolites (such as IL-6, FGF-2, PDGF, MMPs, CXC12, VEGF, FGF, IL8/CXCL8, and PDGF-C) that induce tumor metastasis and tumor cell proliferation." (PMID 35571530, 2022). "Data on the FGF2, FGFBP1, TGFA, TGFBR3, and IGF1R expression levels were analyzed using TIMER 2.0 that matched TCGA tumor tissue with normal tissue." (PMID 36430763, 2022). "This is because previous studies have shown that CAFs regulate angiogenesis by producing proangiogenic factors, such as FGF-2 and VEGF-A, thereby providing essential information for highly proliferating tumor cells." (PMID 35894206, 2022).
tumor (continued). "uPA supports tumor cell proliferation by proteolytically activating various growth factors that include epidermal growth factor (EGF), fibroblast growth factor-2 (FGF-2) and hepatocyte growth factor/scatter factor (HGF-SF)." (PMID 35222418, 2022). "Our bioinformatic analysis showed that tumor angiogenesis-related proteins, including EGFR, FGF1, FGF2, VEGRR2, and PDGFRA, were in the top 15 key targets in the PPI network of QDSJ decoction treating NF2-associated VS." (PMID 36059985, 2022). "MDSCs directly promote tumor angiogenesis by producing VEGF, FGF2, Bv8, and matrix metalloproteinase." (PMID 36006582, 2022). "This inhibition led to the reduced expression of fibroblast growth factor 2 (FGF-2) and FGF-7 leading to suppression tumour growth." (PMID 35814453, 2022). "These secreted chemokines, in turn, promote the recruitment of mast cells in the tumor microenvironment and the expression of mast cell angiogenic factors such as VEGF, TNFα, IL-6, IL-8 and FGF-2, which induce the tumor angiogenesis." (PMID 35805075, 2022). "For example, FGF2 can trigger the formation of new blood vessels to provide nutrients and oxygen for cancers and block programmed cell death through both autocrine and paracrine signaling, which may be a key factor that promotes tumors in the tumor microenvironment." (PMID 36313694, 2022). "PDAC is known to be a hypoxic/fibrotic tumor, which presents rich stroma and secretes proangiogenic factors, namely, VEGF, MMP-9, interleukin-8, and fibroblast growth factor-2." (PMID 35744019, 2022). "Correlation analysis revealed a strong correlation between FGF2 and CD31 expression, suggesting FGF-2-induced tumor angiogenesis." (PMID 35985991, 2022). "In addition, FGF2 and p-FGFR1 were highly expressed in FAPα+ HSCs in the co-opted sinusoidal blood vessels in bevacizumab-resistant HCT116 and HT-29 CRCLM xenografts, indicating that tumor cell–derived FGFBP1 might induce FAPα expression in HSCs by activating the FGF2/FGFR1 signaling pathway." (PMID 35951441, 2022). "Mast cells can stimulate tumor cell expansion by releasing cytokines and growth factors, including fibroblast growth factor-2 (FGF-2), nerve growth factor (NGF), platelet-derived growth factor (PDGF), IL-10, and IL-8, into the tumor stroma." (PMID 36430483, 2022). "One is a tumor-promotive type that produces inflammatory and angiogenic molecules (ROS, VEGF, FGF2, MMP9, IL8, etc.), which induce genetic instability, DNA damage, angiogenesis, and EMT of tumor cells." (PMID 36211375, 2022). "Metformin normalizes the expression of fibroblast growth factor 2 (FGF-2), reduces blood vessel density in obese mice, and restores tumor sensitivity to anti-VEGF therapies." (PMID 36046821, 2022). "M2-mediated tumor growth occurs through the production of growth factors such as VEGF, EGF, FGF2, and TGFβ." (PMID 36568117, 2022). "Neutrophils have been shown to support tumor angiogenesis via the release of numerous pro-angiogenic factors, such as VEGF, FGF-2, oncostatin M, IL-17, MMP-9, Bv8, S100A8/9 alarmins, STAT3, and NETs." (PMID 35158807, 2022). "In EBV-positive tumors, LMP1 can induce the expression of fibroblast growth factor 2 (FGF2) and vascular endothelial growth factor (VEGF) to activate the endothelial cells to support tumor neoangiogenesis." (PMID 35632758, 2022). "Neutrophils can release a series of proteins or chemokines, such as Neutrophil Elastase (NE), myeloperoxidase (MPO), cytokines, fibroblast growth factor-2 (FGF-2), matrix metalloproteinase-9 and VEGF to promote tumor proliferation, invasion and angiogenesis." (PMID 35317078, 2022). "Together, these results reveal upregulated tumor angiogenesis and metastasis in NPC and FGF-2-rich tumors." (PMID 35985991, 2022). "The m5C-related factors form a tumor microenvironment suitable for migration and metastasis of various cancer cells by regulating some known tumor promoters, such as HDGF, TGF-β, FGF2, and G3BP1." (PMID 35464855, 2022).
tumor (continued). "To generalize these findings in FGF-2 expressing tumors, we treated FGF-2–overexpressing and control tumor–bearing mice with clodronate." (PMID 35439170, 2022). "A recent study also suggested that targeting the angiogenic factor, fibroblast growth factor 2 (FGF2), in combination with radiotherapy can increase the iNOS+/CD206+ TAM ratio and improve tumor responses following fractionated radiotherapy." (PMID 36249052, 2022). "To investigate the role of FGF-2 in promoting tumor growth, recruiting TAMs, and metastasis in NPC tumors, we next chose natural FGF-2 high-expressing human NPC 5-8F cells and performed FGF2-specific short hairpin RNA–knockdown (shRNA-knockdown) experiments." (PMID 35439170, 2022). "As a result, knockdown of FGF2 markedly suppressed circulating tumor cells (CTCs) by FACS detection, reduced tumor clone numbers in blood culture, and inhibited pulmonary metastasis." (PMID 35985991, 2022). "Recently, multiple independent studies have reported a critical role of FGF2 in TAM infiltration, which implied a pro-tumor role of FGF2 in tumor progression." (PMID 36189305, 2022). "Many cytokines, such as HDGF, TGF-β, FGF2 and G3BP1, which are validated tumor promoters, participate in cell migration and metastasis induced by the m5C modification, indicating a strong correlation between the RNA m5C level and mobility of cancer cells." (PMID 34512153, 2021). "Colocalization of FGF2 in the nucleus and FGFR1 in the perinuclear region of mesenchymal tumor cells is dependent on co-translocation of syndecan-1." (PMID 34068954, 2021). "Among the pro-angiogenic factors, Fibroblast Growth Factor 2 (FGF2) has been shown to play a relevant role in different tumor types, including MM, its blockade resulting in significant anti-tumor and anti-angiogenic activities." (PMID 34066669, 2021). "Reciprocal interplay between FGF-2 and VEGF-C collaboratively stimulated angiogenesis, intratumoral lymphangiogenesis, tumor growth, and metastasis." (PMID 33921847, 2021). "Potent angiogenic factors include vascular endothelial growth factor (VEGF) and fibroblast growth factor 2 (FGF-2), which are often present in a tumour microenvironment." (PMID 33571850, 2021). "The recruitment and activation of CAFs are mainly controlled by growth factors from tumor cells and immune cells including TGF-β, inflammatory modulators, platelet-derived growth factor (PDGF), and fibroblast growth factor 2 (FGF2)." (PMID 34063627, 2021). "There have been reports that inhibition of FGF2 and its receptor signaling suppresses the proliferation of GBM cells, and that HSPGs in GBM promote tumor invasion." (PMID 34790962, 2021). "This activated phenotype is mediated through multiple factors within the TME, mainly transforming growth factor β (TGF-β), but also fibroblast growth factor 2 (FGF-2) and platelet-derived growth factor (PDGF), paracrine factors secreted mostly by tumour cells." (PMID 34572836, 2021). "The inhibition of MAGL by URB602 decreases xenograft tumor volume through the downregulation of VEGF and fibroblast growth factor-2 (FGF-2)." (PMID 34503163, 2021). "The expressions of CXCR4, FGF-2 and ERK2 in the IR/Contra-tumor group were significantly higher than those in the Sham-IR/Tumor group." (PMID 34764346, 2021). "Fibroblast growth factor 2 (FGF-2) is a member of the FGF family and participates in excessive cancer cell proliferation and tumor angiogenesis." (PMID 33718141, 2021). "Both in vitro and in vivo studies indicated a crosstalk between FGF2 and VEGF that affects blood vessel formation and tumor formation." (PMID 33535617, 2021). "This was explained by the fact that CD14high tumor cells have a higher production of IL6, IL8/CXCL5, CXCL1, CXCL2, M-CSF, VEGF-A, FGF-2 than CD14low tumor cells." (PMID 34572939, 2021).
tumor (continued). "It has also been suggested that lymphocytic response, while potentially eradicating tumour cells, can also aid tumourigenesis by production of several growth promoting signalling molecules (EC GF, VEGF, FGF2, 2, chemokines and cytokines)." (PMID 32661668, 2021). "Tumor cells expressed relatively high levels of EGFR, FGFR1, and FGFR2, while their corresponding ligands, such as COPA, GRN, HBEGF, FGF2, FGF7, and FGF18, were widely expressed in fibroblast cells." (PMID 34459128, 2021). "Mast cells can release various proangiogenic factors, such as VEGF, FGF-2, PDGF, IL-6, tryptase, and chymase, to promote tumor angiogenesis and induce neovascularization." (PMID 34613934, 2021). "MSCs have been found to release many soluble factors that promote tumor survival and its proliferation, including VEGF, FGF-2, PDGF, HGF, BDNF, SDF-1α, IGF-1, IGF-2, TGF-β, and IGFBP-2." (PMID 34112253, 2021). "Members of FGF family (including FGF1, FGF2, FGF4, FGF5, FGF6, FGF7, and FGF9) were reported to be secreted by CAFs and FGFR2 was shown to be a key mediator of tumor niche-derived signals that are responsible for the acquisition of tamoxifen resistance." (PMID 34830951, 2021). "JMJD1A inhibition suppresses tumor growth and angiogenesis and sensitizes cancer cells to VEGF and VEGFR inhibitors by suppressing FGF2, HGF, and ANG2." (PMID 34552922, 2021). "On the other hand, fibroblast growth factor 2 (FGF2), which can induce proliferation of neoplastic cells and hormone independent tumor growth, is a tumor cell survival factor that inhibits cell apoptosis through an autocrine secretory loop." (PMID 34201896, 2021). "FGF2 and VEGF acted synergistically in tumor angiogenesis to accelerate tumor progression, at least on the angiogenic maintenance of tumors in HCC patients." (PMID 33935756, 2021). "FGF2 and activation of FGFR1 regulate immunity in the tumour microenvironment by affecting macrophage programming." (PMID 33655556, 2021). "Scholars have also proposed that FGF-2 and PDGF-BB synergistically regulate the coverage of perivascular cells in tumor vessels." (PMID 34147112, 2021). "Impaired angiogenesis-related signalling pathways: decreased FGF2- and VEGF-dependent Erk1/2 phosphorylation.Decreased tumour vascularization.Reduced tumour growth." (PMID 34858858, 2021). "In this sense, we observed an increase in the expression of VEGF and FGF-2 when cells were transfected with siUGDH and afterward treated with EPI, which are closely involved in the activation of angiogenesis in the tumor environment." (PMID 33572239, 2021). "Significant increases were observed in the expressions of CXCR4, FGF-2, VEGF-A, EGFR and ERK2 (MAPK1) in the IR/Ipsi-tumor group compared to the Sham-IR/Tumor group." (PMID 34764346, 2021). "It has been reported that the expression of growth factors such as VEGF, HGF, bFGF, FGF-2, and transforming growth factor-β/β1 which play essential roles in EMT, bone formation, angiogenesis, tumor angiogenesis, and renal diseases, are regulated by heparanase." (PMID 34681753, 2021). "Once in the tumor, TAMs secrete pro-angiogenic factors such as VEGF-A, TGF-β, fibroblast growth factor-2 (FGF-2), CCL18, semaphorin 4D (Sema4D), adrenomedullin (ADM), and placental growth factor (PlGF)." (PMID 33783686, 2021). "Tumor cells can secrete different pro-angiogenic factors, such as VEGF, FGF-2 and EGF, among others, capable of promoting the migration of endothelial cells and the formation of blood vessels." (PMID 33572239, 2021). "TAMs sense hypoxia in avascular areas of tumors and react in turn by releasing pro-angiogenic factors such as FGF-2, TNF-α, and VEGFs, which again promotes tumor oxygenation by the direct recruitment of endothelial cells." (PMID 33747916, 2021). "A disulfide-stabilized diabody (ds-Diabody) against FGF-2 was produced in Pichia pastoris (GS115) by fermentation and the anti-tumor activity was analyzed." (PMID 33718141, 2021).
tumor (continued). "The bi-directional cross-talk between CAF and tumor cells involves putative secretory signaling proteins such as TGF-beta 2, FGF2 (from CAF), and FGFR1 (from tumor cells)." (PMID 34502029, 2021). "We detected the endothelial LAT1 expression not only in tumor tissues but also in in vitro HUVEC cultures and in the endothelial cells from ex/in vivo angiogenesis assays, in which VEGF-A and FGF-2 were supplemented to culture media." (PMID 33256804, 2020). "To examine the activation status of FGFR2 and the levels of FGF2 and FGFR2 in Mock and VEGFR2-Fc–expressing tumors, we conducted Western blot analysis of tumor lysates from tumors resected at a volume of ~500 mm3." (PMID 32076044, 2020). "In particular, FGF-2 expression is high in the tumor stroma, including inflammatory cells, myofibroblasts, and endothelial cell, suggesting that FGF-2 can modulate tumor progression." (PMID 32456056, 2020). "Among the candidate list we identified (MMP10, IL1α, TIE1, FGF2, BMP6), IL1α has been reported to be released by both stromal cells and PC cells, and to promote tumor growth in PDAC." (PMID 33105540, 2020). "Maspin, a tumor suppressor, has been shown to inhibit HUVEC migration under FGF2 stimulation through an integrin β1 signaling pathway." (PMID 33154757, 2020). "Therefore, it can be speculated that FGF2 may be a promoting effect on the tumor progression." (PMID 33381388, 2020). "Fibroblast growth factor-2 (bFGF) has a wide range of biological activities, including promoting wound healing, promoting neovascularization, and repairing damaged blood vessels, and is highly expressed in many tumor tissues, and its expression may be related to the formation of tumor blood vessels." (PMID 32802112, 2020). "Our study reveals a new role for FGF2 in pericytes, and activation of the FGF signaling pathway in tumor vessels in anti-VEGF therapy–resistant tumors." (PMID 32076044, 2020). "Recently, estrogens have been shown to mediate FGF2/FGFR1 paracrine activation through the G protein estrogen receptor (GPER), which coupled CAFs to breast cancer cells towards migratory and invasive tumor cell responses." (PMID 33081025, 2020). "In particular, several preclinical studies demonstrated that the angiogenesis blockade in tumor-bearing mice upregulates expression of PlGF, VEGF, FGF-2, and other angiogenic factors." (PMID 32456056, 2020). "The tumor tissues in the groups E10 and G11 were paraffin-embedded and the sections were immunohistochemically stained with antibodies for EGFL6, FGF-2, PDGFβ, VEGFA, CD31, and LYVE1." (PMID 32983976, 2020). "Fibroblast growth factor 2 (FGF2) can synergize with VEGF-C signaling and induce lymphatic vessel formation and tumor metastasis." (PMID 33172072, 2020). "Activation of the FGF2/FGFR autocrine loop in IM-treated GISTs was also revealed by in vivo studies illustrating nuclear localization of FGF-2 in GIST xenografts after IM treatment and tumor specimens of GIST patients who received IM-based therapy." (PMID 32599808, 2020). "The binding of FGF2 to FGFR can activate PI3K/AKT signaling and affect the cytotoxicity of chemotherapeutic drugs, ultimately influencing the sensitivity of tumor cells to chemotherapeutic drugs." (PMID 31959735, 2020). "In the case of LMP1, different cargos have been found to be packaged into EVs, including EGF receptor (EGFR), fibroblast growth factor 2 (FGF-2), PI3K, and HIF1α, which play major roles in angiogenesis, tumor growth, and metastasis." (PMID 32546618, 2020). "Whilst MC38 cells were tested in syngeneic mice, the combination of irradiation and anti-FGF2 antibody also effectively prolonged survival of immunosuppressed mice bearing SW1222 and HT29 subcutaneous tumours." (PMID 32792542, 2020). "Conversely, mediators released by MC such as FGF-2, NGF, PDGF, VEGF, IL-8, and IL-10 promote the expansion of tumor cells." (PMID 31256327, 2020).